PRDM16 (PR/SET domain 16)
Diseases named in the same sentence as PRDM16 in open-access papers (continued):
Sharing a sentence is not in itself a finding about the gene and the disease.
leukemia (23 papers, 2008 to 2026). A malignant (clonal) hematologic disorder, involving hematopoietic stem cells and characterized by the presence of primitive or atypical myeloid or lymphoid cells in the bone marrow and the blood. "In cancer, alterations in PRDM16 expression or function have been associated with various leukemias as aberrant PRDM16 activity can disrupt normal gene expression and contribute to oncogenesis." (PMID 39765675, 2024). "Recently, Prdm16 loss-of-function has been shown to play an instrumental role in leukemia driven by the MLL fusion oncoprotein." (PMID 36828547, 2023). "This transcript is predicted to encode a truncated protein similar to that expressed in human leukemias with PRDM16 mutations." (PMID 19461887, 2009). "In the blood system, overexpression of PRDM16 promotes leukemia development​, which highlights the importance of targeted delivery." (PMID 40758676, 2025). "Different PRDM16 transcripts play different roles in leukemia hematopoiesis and the inflammatory reaction." (PMID 38674344, 2024). "In mouse models, forced overexpression of murine PRDM16, especially the short isoform, is able to transform hematopoietic stem cells and induce a fatal, transplantable leukemia." (PMID 37236968, 2023). "The PR domain of PRDM16 was shown to be essential in suppressing MLLr1 leukemia via intrinsic H3K4 methylation activity." (PMID 33597191, 2021). "Successively, additional PRDM16 translocation partners, fusion transcripts and other rearrangements have been detected in leukemia cases with a poor prognosis, most of them showing an upregulation of this gene as a common feature." (PMID 32290321, 2020). "Through this technique, we identified recurrent alterations in genes DMBT1, KIAA0125 and PRDM16; these alterations were verified by qPCR and confirmed the possible involvement of these genes in the development of leukemia, especially in ALL." (PMID 32607130, 2020). "Prdm16 has well characterized functions in adipogenesis, leukemia pathogenesis, and neuronal stem cells maintenance." (PMID 25330008, 2014). "Prdm16, originally named Mel1, was first identified as being expressed at highly elevated levels in leukaemia." (PMID 19050759, 2008). "In addition its involvement in leukemia, several studies have subsequently shown that Prdm16 controls brown fat cell differentiation as well as dedifferentiation of white fat to beige fat." (PMID 36828547, 2023). "Also, the high expression level of PRDM16 was reported to involve pathological progression and poor prognosis of AML, and the downregulation of PRDM16 mRNA had an anti-leukemia effect in mice." (PMID 36543880, 2023). "The mouse model of conditional Prdm16 deletion elucidated the role of these two isoforms in normal and leukemic hematopoiesis and identified sPrdm16 as one of the drivers of prognostically adverse inflammation in leukemia." (PMID 32290321, 2020). "In another study, PRDM16 knockdown induced cell proliferation in rhabdoid tumor cells, suggesting that PRDM16 may be an oncogene in leukemia development, although in other tumor types PRDM16 has a controversial role." (PMID 32607130, 2020). "This analysis also pointed to the higher expression of several other genes normally deregulated in a wide spectrum of leukaemias, including genes that act as transcriptional regulators (PRDM16 and NFIX) and a gene that influences proliferative advantage and survival (IGFBP2)." (PMID 32103106, 2020). "It has been reported that the short variant of PRDM16, PR-lacking PRDM16 was involved in several hematological malignancies through blocking differentiation of progenitor cells and promoting growth of leukemia cells." (PMID 30683132, 2019). "Because the MLL gene encodes a histone-3 Lysine-4 (H3K4) methyltransferase that is critical in promoting gene expression during hematopoiesis, it has been postulated that Prdm16 might suppress leukemia pathogenesis owing to its ability to drive heterochromatin formation." (PMID 36828547, 2023).
leukemia (continued). "Additionally, amplification of PRDM16 was found in leukemia, osteosarcoma, and gastric cancer, and reduced expression of PRM16 was observed in uterine leiomyosarcoma and NSCLC, which elucidated PRDM16 and also functions as an oncogene or TSG in several cancers as MECOM." (PMID 35174083, 2022). "We recently performed RNA sequencing in several molecularly well-defined AML subgroups and saw a clear differentiation of low (e.g. CBF-leukemias, CEBPA-bZIP-Indel) and high PRDM16 expression (NUP98-NSD1; UBTF-TD)." (PMID 41566085, 2026). "We identified differential methylation of genes that have been related to cancers such as lymphoma (WNT6, TP73, and CD37), leukaemia (MEIS1, HOXA4, and HOXA5) or neuroblastoma (TP73), as well as genes related to cardiovascular diseases (UCN, PRDM16, TCAP, ALOX5)." (PMID 35354948, 2022). "Prdm16 was first identified in leukemia, where truncation mutants lacking functional domains behaved as oncogenic, providing the first indication that Prdm16 might function as a tumor suppressor." (PMID 36828547, 2023). "Moreover, certain mutations that constitutively activate Notch1 protein cause leukaemia; although this is usually T-cell acute lymphoblastic leukaemia rather than the AML associated with Prdm16." (PMID 19050759, 2008).
cardiomyopathy (22 papers, 2014 to 2026). A disease of the heart muscle or myocardium proper. "This novel pathogenic PRDM16 variant has potential utility in diagnosis and prognosis and underscores the critical and unique role of PRDM16 in human cardiomyopathy." (PMID 41584850, 2026). "The consistency with segregation of the variant and the disease in the family suggests this novel PRDM16 germline variant is likely responsible for the family's extensive history of cardiomyopathy and heart failure." (PMID 41584850, 2026). "Together, these studies have unequivocally demonstrated the link between heterozygous PRDM16 mutations and phenotypically diverse cardiomyopathies." (PMID 40439125, 2025). "It was demonstrated that PRDM16 plays a role in maintaining the transcriptome properties of dense cardiomyocytes, acting to activate dense cardiomyopathy genes while repressing those associated with left ventricular trabecular cardiomyopathy." (PMID 41420191, 2025). "While LVNC was the most common clinical feature, the cardiac phenotypes observed due to PRDM16 deficiency span the entire spectrum of cardiomyopathies, including conduction abnormalities." (PMID 40439125, 2025). "Recently, sexual dimorphism in cardiomyopathy patients because of PRDM16 mutations has been reported, with females having a higher chance of developing cardiomyopathy." (PMID 39304345, 2024). "We characterize the heart of heterozygous Prdm16csp1/wt mice in depth to assess the impact of monoallelic germline Prdm16 inactivation, the situation seen in patients with PRDM16 associated cardiomyopathy." (PMID 37842925, 2024). "Normal viability, myocardial hypoplasia, and diminished cardiac performance due to monoallelic Prdm16 inactivation suggest that Prdm16csp1/wt mice are a suitable model to explore early pathophysiological changes in PRDM16 associated cardiomyopathy." (PMID 37842925, 2024). "Overall, this study establishes heterozygous Prdm16csp1/wt mice as a model for early molecular pathomechanistic events in the development of the PRDM16 associated cardiomyopathy." (PMID 37842925, 2024). "We have also shown that mice with cardiac deletion of Prdm16 (Prdm16flox/flox; Myh6-Cre) experience dysfunctional cardiac conduction and cardiomyopathy-associated phenotypes, suggesting that impairments in ion homeostasis underlie these phenotypes." (PMID 35862303, 2022). "A recent study of the patient cohort with PRDM16 loss in the setting of 1p36 deletion syndrome suggests that PRDM16 loss may be associated with sex-dependent cardiomyopathy and cardiac mortality." (PMID 41584850, 2026). "PRDM16, a transcriptional regulator with reported histone methyl-transferase activity, hasbeen identified as a critical factor regulating human adipose tissue development,hematopoietic development and is associated with cardiomyopathies." (PMID 38595939, 2024). "In humans, PRDM16 mutations have been identified as a cause of cardiomyopathy." (PMID 39351529, 2024). "Indeed, mutations in PRDM16 have been described in patients with cardiomyopathy and left ventricular non‐compaction." (PMID 36369750, 2023). "Thus, using adult mice (aged 5 months) that harbor cardiac-specific Prdm16 conditional knockout alleles, we analyzed changes in BP to determine the underlying mechanisms of BP-associated changes in a murine model with HF or cardiomyopathy." (PMID 35862303, 2022). "Furthermore, the consistent presence of the PRDM16 variant in affected family members, and its absence in non-affected family members, combined with a strong maternal family history of cardiomyopathy, provides compelling support for the pathogenicity of the PRDM16 variant." (PMID 41584850, 2026). "Hence, genetic testing, coupled with research aimed at a better understanding of the molecular underpinnings of PRDM16-associated cardiomyopathies, may lead to therapeutic advances, improved patient health care and better clinical outcomes." (PMID 40439125, 2025).
cardiomyopathy (continued). "Thus, deficiency of PRDM16 in CMs caused severe signs of cardiomyopathy early on." (PMID 39304345, 2024). "Elucidation of pathophysiological pathways involving PRDM16 in human heart development and maintenance of normal function is essential for developing drugs targeting PRDM16-related cardiomyopathy." (PMID 41584850, 2026). "PRDM16 is a zinc-finger transcription regulator and has been suspected to be responsible for the cardiomyopathy features in the 1p36 deletion syndrome." (PMID 41584850, 2026). "Recent research has demonstrated that PRDM16 is involved not only in fat metabolism but also in diabetes, cardiomyopathy, cancer, aneurysm, and renal fibrosis [21,25,]." (PMID 39549609, 2024). "We and others have reported results that implicate Prdm16 in certain types of cardiomyopathy, HF, and cardiac conduction abnormalities." (PMID 35862303, 2022). "While none of these specific variants have been described as pathogenic, PRDM16, SYNM and TTN are well-known cardiomyopathy-associated genes." (PMID 35260914, 2022). "Nonetheless, it has become increasingly clear from other study cohorts that impaired PRDM16 signalling may not only predispose to LVNC, but also to other types of cardiomyopathy." (PMID 40439125, 2025). "Finally, we also identified four variants of uncertain significance in cardiomyopathy-associated genes (TNNT2, PRDM16, LDB3, and SDHA) in three fetuses." (PMID 33553264, 2020). "Importantly, these studies—which have unravelled key functions of PRDM16 at different time points of cardiac development—do not reflect patients with PRDM16-related cardiomyopathy that are heterozygous for the PRDM16 mutation." (PMID 40439125, 2025). "Overall, these studies evidenced the indispensable role of PRDM16 in cardiac development and function, and the variety of cardiac phenotypes seen in the distinct models likely reflects the broad clinical landscape seen in PRDM16-related cardiomyopathy patients." (PMID 40439125, 2025). "Interestingly, we could detect a DMR in the gene PRDM16, a gene shown to be involved in cardiomyopathy, which was consistent with the symptoms experienced by the patients (i.e., GEO ID: GSM2366439, GSM2366759, GSM2366459, GSM2366724)." (PMID 36527161, 2022). "However, although there might be a role for PRDM16 in cardiac development, its role as a cardiomyopathy gene has subsequently been questioned." (PMID 28228157, 2017). "In the literature from 22 to 27% of patients presented cardiomyopathy and two critical regions for cardiomyopathy have been described one of which includes PRKCZ, SKI, and PRDM16." (PMID 36369750, 2023). "Nevertheless, there is no obvious sex bias in our reported family in terms of PRDM16-related cardiomyopathy." (PMID 41584850, 2026). "SNP rs4483351 was located on PR/SET domain 16 gene (PRDM16, OMIM accession number: 605557), which was found to have connection with cardiomyopathy, thus it might could play an important role in regulating blood pressure." (PMID 34586716, 2021). "Interestingly, three deletions from our cohort, encompassing PRDM16 but no SKI did not present cardiomyopathy." (PMID 36369750, 2023).
gastric cancer (15 papers, 2018 to 2025). A primary or metastatic malignant neoplasm involving the stomach. "In gastric cancer, exosomal ciRS-133 promotes white adipose tissue browning by inhibiting miR-133 and activating PRDM16, thereby reducing the oxygen consumption of the gastric cancer microenvironment and promoting tumor growth." (PMID 34249673, 2021). "Gastric cancer-derived exosomal circRNA ciRS-133 promotes white adipose browning by targeting the miR-133/PRDM16 pathway." (PMID 33867829, 2021). "Otherwise, a more recent study showed that miR-214 was able to inhibit PRDM16 expression thus promoting the proliferation and migration of gastric cancer cells and enhancing the Warburg effect." (PMID 32290321, 2020). "Additionally, in gastric cancer cells, PRDM16 has been found to inhibit TGF-β signaling by interacting with Ski oncogene, a known repressor of TGF-β signaling." (PMID 39625782, 2024). "Exosomes from gastric cancer (GC) cells deliver ciRS-133 to adipocytes, which inhibits the expression of miR-133 and activates the expression of PRDM16 and UCP1, thereby accelerating the metabolic rate of mature adipocytes, increasing oxygen consumption and heat production." (PMID 33912560, 2021). "Then, a recent evaluation found that exosomes derived from gastric cancer cells could deliver the circular RNA ciRS-133 into preadipocytes, promoting the differentiation of preadipocytes into brown-like cells through PRDM16 activation and miR-133 suppression." (PMID 32290321, 2020). "Previous studies have demonstrated that miR-214-3p can regulate the proliferation, apoptosis, and metastasis of gastric cancer cell lines (e.g., SGC-7901, BGC-823, and GC9811) through distinct target genes, including A2AR, PRDM16, PTEN, and Dact2." (PMID 41318488, 2025). "In gastric cancer cells, miR-214-3p was shown to induce the Warburg effect by directly targeting genes for the adenosine A2A receptor (A2AR) and PR/SET domain 16 (PRDM16) and promoting migration and cell proliferation." (PMID 36768818, 2023). "Previously, MEL1/PRDM16, together with SKI, was aberrantly expressed by chromosomal co-amplification of 1p36.32 in gastric cancer cells." (PMID 32290321, 2020). "The ciRS‐133 is up‐regulated in gastric cancer (GC), enters pre‐adipocytes through exosomes derived from GC cells and then promotes the differentiation of pre‐adipocytes into brown‐like cells by targeting the miR‐133/PRDM16 axis." (PMID 32578911, 2020). "The same researcher reported rearrangement of PRDM16 and EVI1 genes showed poor prognosis in AML cancer-cases, suggesting that PRDM16 involves in development of gastric cancer." (PMID 30212456, 2018). "For example, in CD4+ T-cells, BCL9 for B-cell acute lymphoblastic leukemia (B-ALL); GAS7 and PRDM16 for Acute myelogenous leukemia (AML); ESR1 for breast cancer; and GRIN2A for colorectal, lung, and gastric carcinoma were differentially methylated between PWH and PWoH." (PMID 38466776, 2024).
diabetes (14 papers, 2014 to 2025). "Differential methylation of PRDM16 is associated with maternal diabetes in blood of children and in umbilical cord tissue, and plays an important role in pancreatic development." (PMID 35500004, 2022). "Although recent studies indicate that epicardial adipose tissue expresses brown fat-like genes, such as PGC1α, UCP1 and PRDM16, the association of these genes with type 2 diabetes mellitus (DM2) in coronary artery disease (CAD) remains unknown." (PMID 27542888, 2016). "In isolated APCs, the expression of PRDM16, a marker for brown/beige adipose progenitors, also exhibited a significant adipose source by diabetes interaction, with IMAT DIA APCs having significantly lower expression than IMAT ND APCs." (PMID 41245395, 2025). "Interestingly, the beneficial effect of bone marrow fat on the regulation of bone mass is presented through the expression of brown adipocyte gene markers (Ucp1, Prdm16), and this ability diminishes with a decrease in metabolic capacity due to age or diabetes." (PMID 35733771, 2022). "Genetic modification of mice revealed that PRDM16 is critical for pancreatic development, suggesting that PRDM16 may be a regulatory gene for pancreatic development and related diseases such as diabetes." (PMID 35462933, 2022). "Chronic training increased the mRNA level of PGC-1α of SAT by 1.2-fold and 1.6-fold in the control group and the pre-diabetes group, respectively, whereas no significant changes neither in the brown-fat-selective gene Prdm16 or other known browning genes TBX1, TMEM26, and CD137 for both groups." (PMID 33922998, 2021).
Insulin resistance (13 papers, 2014 to 2025). Increased resistance towards insulin, that is, diminished effectiveness of insulin in reducing blood glucose levels. "Accordingly, inhibition of beige adipocyte function by conditional deletion of Prdm16 caused severe insulin resistance and hepatic steatosis in mice receiving HFD." (PMID 34846543, 2022). "Deacetylation of Lys268 and Lys293 on PPARγ induced by SIRT1 recruits the BAT program coactivator Prdm16, leading to the selective induction of BAT genes and repression of WAT genes associated with insulin resistance." (PMID 34421358, 2021). "SirT1-dependent deacetylation of Lys268 and Lys293 is required to recruit the BAT program co-activator Prdm16 to Pparγ, leading to selective induction of BAT genes and repression of visceral WAT genes associated with insulin resistance." (PMID 25514854, 2014). "Similar to PRDM16, EHMT1 fat-specific deficient mice show obesity and insulin resistance." (PMID 30186237, 2018). "SIRT1 binds and deacetylates PPARγ, which helps recruit the BAT program coactivator PRDM16 to PPARγ, leading to selective induction of BAT genes associated with browning of white adipocytes and repression of visceral WAT genes associated with insulin resistance." (PMID 35743009, 2022). "Germline deletion of IL-10 protects mice from insulin resistance and diet-induced obesity (DIO), by increasing Ucp1, PR/SET domain 16 (PRDM16), and other thermogenic genes in adipocytes in the white adipose tissue (WAT)." (PMID 33351782, 2021). "Mice without PRDM16 in their white fat cells develop severe insulin resistance and subcutaneous macrophage accumulation on a high-fat diet (HFD), resembling the phenotype of visceral obesity." (PMID 34846543, 2022). "Transgenic and tissue specific animal models show that increased expression of PRDM16 in rodent inguinal white adipose tissue (iWAT) and in mature adipocytes promotes beige adipocyte commitment and prevents HFD-provoked weight gain and systemic insulin resistance." (PMID 30186237, 2018).